NF2 (NF2, moesin-ezrin-radixin like (MERLIN) tumor suppressor)
Diseases named in the same sentence as NF2 in open-access papers (continued):
Sharing a sentence is not in itself a finding about the gene and the disease.
meningioma (continued). "And Neurofibromin (NF2) deficiency and low E-cadherin (CDH1) levels have been shown to increase ferroptosis vulnerability in meningiomas." (PMID 37091802, 2023). "Meningiomas are common central nervous system tumors, and an NF2 inactivation is an early event in the development and progression of meningiomas." (PMID 36835189, 2023). "Currently, there is an ongoing multi-arm study (NCT02523014) investigating abemaciclib in recurrent meningioma patients with alterations in the CDK pathway or altered NF2 gene." (PMID 38017560, 2023). "NF2 mutant meningiomas, for instance, typically originate from lateral segments, along the cerebral convexities or skull base." (PMID 37010677, 2023). "We also compared the mRNA expression of related proteins with that of immunogenic meningioma and found that tumours in NF2 patients also showed higher expression of these mRNA than sporadic NF2-altered tumours." (PMID 37752594, 2023). "Herein, we present a long-term follow-up clinical/molecular analysis of meningiomas in NF2 patients compared with that of sporadic NF2-altered meningiomas." (PMID 37752594, 2023). "All variables of meningiomas in patients with NF2 were compared with those in 189 sporadic NF2-altered meningiomas in 189 patients." (PMID 37752594, 2023). "The rate of S100 positive cases was almost 3 times as high in meningiomas from patients suffering from NF2 (11.0% vs. 4.1%, p < 0.0001)." (PMID 35838837, 2023). "As such, the site of involvement determines the severity and type of symptoms of NF2-related meningioma." (PMID 37217995, 2023). "Prior work has shown that primary atypical meningiomas, comprised mostly of NF2 mutants with genomic instability or recurrent SMARCB1 mutations, display a hypermethylated phenotype due to increased polycomb repressive complex 2 (PRC2) activity." (PMID 36937440, 2023). "This strategy can be applied for refractory benign brain tumors including Grade 2 meningiomas, NF2-related schwannomas, and PitNET with cavernous sinus invasion." (PMID 37629179, 2023). "The immunogenic group consisted mainly of NF2-altered meningiomas and showed benign clinical outcomes." (PMID 37752594, 2023). "The anatomical distribution of meningiomas differed between NF2 patients and sporadic case with NF2 alterations, especially in the frequency of the falx meningiomas (22.0% in meningiomas of NF2 patients, 8.4% in sporadic NF2-altered tumours, p = 2.2 × 10–16)." (PMID 37752594, 2023). "Indeed, it seems reasonable to assume that at least part of the meningioma cases previously believed to be caused by yet unrecognized genetic factors might in fact contain BRAF/NF2/PIK3CA/SMO mutations at frequencies inferior to the limits of traditional detection methods." (PMID 38259646, 2023). "The bar graph for IHC in each case shows that many cases also showed rich immune cell infiltration in sporadic NF2-altered meningiomas." (PMID 37752594, 2023). "Our study showed that most grade I NF2-altered meningiomas showed immune cell infiltration, which is consistent with the latest reports." (PMID 37752594, 2023). "Meningiomas in the second group feature NF2 inactivation, are devoid of chromosomal instability, are enriched in immune cells, and have an intermediate prognosis." (PMID 37296907, 2023). "In approximately 40–60% of sporadic meningiomas and 80% of high-grade meningiomas, inactivation of NF2 account for tumor development and progression." (PMID 36641486, 2023). "Among 37 NF2 patients with meningiomas, germline NF2 alterations were identified in 18 patients (48.6%), including truncating mutations (9, 24.3%), large deletions (2, 5.4%), splice-site mutations (6, 16.2%), and missense mutations (1, 2.7%)." (PMID 37752594, 2023). "Patients who harbor NF2 mutant meningiomas are typically male, present with preoperative seizures and have larger tumors." (PMID 37010677, 2023). "WHO grade I meningiomas in patients with NF2 were more frequent than in sporadic NF2-altered meningiomas (92.9% vs. 80.9%)." (PMID 37752594, 2023).
meningioma (continued). "MG2 meningiomas, primarily “NF2-wildtype”, had transcriptomic pathways involved in vasculature development and angiogenesis." (PMID 36840836, 2023). "NF2, TERT, SMARCB1, SMARCE1 and BAP1 have been associated with higher grade meningioma and poor prognosis." (PMID 36882706, 2023). "Approximately half of NF2 cases have meningiomas that usually present as multiple meningiomas with considerable morbidity due to seizures, paralysis, and headaches." (PMID 37217995, 2023). "The mean annual growth rate (cm3/year) was 1.0 ± 1.8 in all meningiomas with NF2 patients and 3.7 ± 2.4 in resected meningiomas with NF2 patients (p = 3.8 × 10–6)." (PMID 37752594, 2023). "The age at the surgery in NF2 patients was younger than that in sporadic NF2-altered meningiomas (42.5 ± 16.8 vs. 60.3 ± 13.2, p = 4.1 × 10–8)." (PMID 37752594, 2023). "High immune activity in sporadic NF2-altered meningiomas has only been reported by the latest studies using single nuclear/cell RNA sequencing." (PMID 37752594, 2023). "We addressed this issue by molecular background analysis of meningiomas in NF2 patients with bulk RNA-seq." (PMID 37752594, 2023). "TEAD palmitoylation inhibitors prevented the growth of NF2-null schwannoma and NF2-null meningioma cells in vitro and in a mouse model." (PMID 38001599, 2023). "To understand how tumor-associated mutations cause meningioma growth and to assess the differences between the most common groups of meningiomas, we compared transcriptomes of NF2 and TRAF7 meningiomas." (PMID 36937440, 2023). "Compared with meningiomas in NF2 patients, recent molecular analyses have established that sporadic meningiomas are not genomically homogenous but have various genetic, epigenetic, and transcriptomic profiles." (PMID 37752594, 2023). "The analysis revealed that meningiomas with NF2 gene inactivation expressed higher levels of BCL2 and GLI1 compared with tumors harboring TRAF7 missense mutations." (PMID 36937440, 2023). "A series of papers subsequently described that non-NF2 meningiomas were subdivided into genomic groups defined by their specific somatic mutations." (PMID 36937440, 2023). "Meningiomas in the second group have an intermediate prognosis and are characterized by NF2 alterations, mild chromosomal instability, and enrichment in immune cells." (PMID 37296907, 2023). "MC ben-3, MC int-B, and MC-mal had similar proportions of NF2-mutant meningiomas ranging from 31 to 35% of meningiomas in each class, while 53% of meningiomas in MC int-A were NF2-altered." (PMID 36840836, 2023). "In this study, we aimed to investigate the clinical significance of NF2 alteration in the prognosis of WHO grade I meningiomas." (PMID 35570314, 2022). "In contrast to AKT1-mutant meningiomas, a substantial proportion of NF2-mutant meningiomas developed in the dorsal or dorso-lateral location to the spinal cord (59.3%, p = 0.0043, online resource)." (PMID 35943573, 2022). "Other tumor indications with Hippo-YAP1 pathway alterations have also been reported, including tumors with YAP1 amplifications such as cervical cancer or tumors with NF2 deletions such as renal cell carcinoma and schwannomas meningiomas." (PMID 35689194, 2022). "Compared to NF2-wt meningioma, NF2 mutant meningiomas was detected with a higher proliferation index (Ki-67 labels) and often manifested in comparatively larger tumor size." (PMID 36267986, 2022). "NF2 alteration is the most commonly–found genetic abnormality in meningiomas and is known to initiate events for aggressive-type meningiomas." (PMID 35570314, 2022). "Genomic analyses applied to aggressive meningiomas have also identified 3 distinct groups of meningiomas organized by NF2 status: NF2-mutant, NF2-agnostic, and NF2-wild type." (PMID 36686824, 2022). "SMARCB1-NF2 mutant meningiomas account for 6.8% of all NF2-mutant meningiomas and are preferential localized in the midline dura (falx) or in the anterior convexity." (PMID 35049691, 2022).
meningioma (continued). "Further, a phase II trial revealed another MEK1/2 inhibitor, selumetinib, to have an effect on NF2-related meningiomas (NCT03095248)." (PMID 35712491, 2022). "Strong expression of SSTR2A receptors, inhibition of the osteoglycin/mTOR pathway, and activation of NF2 signaling promote apoptosis in malignant meningioma cells." (PMID 35712491, 2022). "Recently, YAP1-fusions have been identified for the first time as potential NF2-independent oncogenic drivers in the development of meningiomas in pediatric patients." (PMID 36292056, 2022). "Cre/lox-mediated knockout of NF2 resulted in a 4-fold increased rate of meningioma formation within a year in Ptprj knockout mice compared to wild-type (WT) littermates." (PMID 36611803, 2022). "Molecular analysis revealed that there were 152 NF2 meningiomas (54.1%) and non-NF2 meningiomas: 45.9% (129 cases) including “AKT1”: 11.4% (32 cases), “KLF4”:5.7% (16 cases), “POLR2A”:16 cases (5.7%), “SMO”: 0.7% (2 cases), and others:22.1% (62 cases)." (PMID 35570314, 2022). "CUDC907 was pre-clinically evaluated in several cell culture models as well as in two NF2 schwannoma and meningioma models by the Synodos for NF2 Consortium." (PMID 35875610, 2022). "Silencing MEF2C, the expression levels of NF2 and E-cadherin in meningiomas decreased, which inhibited the growth of meningiomas mediated by ferroptosis." (PMID 35530363, 2022). "Neurofibromatosis 2 (NF2) alteration is the most common genetic driver in sporadic meningiomas and is known to initiate events for aggressive-type meningiomas." (PMID 35570314, 2022). "This retrospective study included 105 patients with meningiomas, including 60 NF2-mutant samples and 45 wild-type samples." (PMID 36267986, 2022). "The NF2/PIK3CD2B/ SMAD4 mutant IVM featured 1p LOH, which was previously linked to meningioma recurrence." (PMID 35049691, 2022). "But especially patients with WHO grade II and III meningiomas and neurofibromatosis type 2 (NF2), who frequently develop many intracranial meningiomas, are subjects that need to be further assessed regarding this targeted therapy option." (PMID 33899156, 2022). "The 2021 WHO classification criteria incorporates 10 genes that are frequently altered in meningiomas, including NF2, AKT1, TRAF7, SMO, PIK3CA." (PMID 35712492, 2022). "The tumors differ significantly between NF1 and the latter two variants, whereas both NF2 and SWN have multiple schwannomas and meningiomas as defining features." (PMID 35053664, 2022). "Three meningiomas (50%) had NF2 alterations, consisting in truncating (24M and 27M) or frameshift (26M) mutations." (PMID 35049691, 2022). "It shows alterations in more than half of meningiomas, especially in benign tumors, with a large proportion of deletions of chromosome 22 occurring in the neurofibromatosis type 2 gene (NF2) region, which contributes to the development of meningiomas." (PMID 35712491, 2022). "The median age of patients with AKT1E17K mutations (71 years old) was significantly higher when compared with patients with NF2-mutant meningiomas (65.5 years-old, p = 0.032)." (PMID 35943573, 2022). "Along the skull base, NF2-mutant meningiomas show lateral to medial gradient, originating along the lateral sphenoid wing, invading the bone." (PMID 34846640, 2022). "A tumor location in the thoracic spine was significantly more common in NF2-mutant meningiomas (75%) than in their AKT1-mutant counterparts (26.6%) (p = 0.0034)." (PMID 35943573, 2022). "A recent study of 469 meningiomas suggested a 22x higher recurrence rate in aggressive subgroups (NF2, PI3K, HH, TRAF7) compared to others (KLF4, POLR2A, SMARCB1)." (PMID 35213082, 2022). "This also accounts for the different meningioma subtypes when the biallelic NF2 gene is inactivated." (PMID 34674099, 2022).
meningioma (continued). "Correspondingly, even if GTR is achieved in WHO grade I meningiomas, this study suggested that close follow-up and proactive measures should be considered in cases characterized by NF2 alteration, supratentorial location, and high Ki-67 index." (PMID 35570314, 2022). "Based on this analysis, cases with NF2 alteration/22q loss were classified into molecular groups (MGs) 1, 3, and 4, among which the prognosis for recurrence in MG3 and 4 meningiomas is reported to be poor." (PMID 35804955, 2022). "In this study, we investigated the utility of a radiomics signature based on multiparametric MRI as a preoperative and noninvasive biomarker of NF2 status in meningiomas." (PMID 36267986, 2022). "Among the six non-NF2 mutant subtypes, the TRAF7 mutated alone subtype is the most common in 25% of sporadic meningiomas and is associated with a higher grade." (PMID 36033542, 2022). "Noteworthy, none of the cases had gene mutations typically observed in skull base meningiomas and involving AKT1, PIK3CA and SMO, while one case had co-occurring NF2 and SMARCB1 mutations previously found in sagittal meningiomas." (PMID 35049691, 2022). "NF2 inactivation was the most common alteration in meningiomas and played an important role in tumor progression." (PMID 36267986, 2022). "In their cohort of high grade meningiomas, most tumors were characterized by NF2 mutations, with very few tumors having mutations in TRAF7, KLF4, AKT1 and SMO, suggesting that high grade meningiomas have few targetable genetic mutations." (PMID 35402234, 2022). "These discrepancies occurred in both NF2 wild-type as well as NF2-altered meningiomas, although higher grade copy number alterations were more common in NF2-altered meningiomas." (PMID 35299730, 2022). "The most frequent CNV in sporadic meningiomas is chromosome 22q deletion, which contains NF2 and SMARCB1, among others." (PMID 34846640, 2022). "We performed a long-term follow-up study to validate the effect of EOR, the significance of NF2 alteration, and tumour anatomical location on meningioma recurrence." (PMID 35570314, 2022). "Pre-clinical studies of cultured meningioma cell lines from NF2 found targeting of the histone deacetylase (HDAC)resulted in decreased AKT activation and decreased cellular growth, as well as, decreased tumor size in mouse models." (PMID 36033542, 2022). "Although the role of pharmacotherapy is currently ill-defined, a phase II trial is currently investigating the efficacy of targeted therapies in meningiomas harboring specific, targetable alterations, including SMO/AKT/NF2/CDK mutations (NCT02523014)." (PMID 35049691, 2022). "An analysis of promoter methylation in NF2 altered vs wildtype yielded 98 gene promoters that were hypermethylated in NF2 altered meningiomas relative to wildtype tumors and 325 gene promoters that were hypomethylated in NF2 wildtype tumors." (PMID 35769412, 2022). "Both studies identified so-called “benign” or “Merlin-intact” meningiomas that have at least one functional copy of NF2, limited genomic instability, and favorable outcomes." (PMID 36315366, 2022). "The study revealed the significance of NF2 mutation and/or 22q loss in WHO grade I meningiomas in predicting recurrence, which was intriguingly reinforced by tumour anatomical locations." (PMID 35570314, 2022). "Most meningiomas carry mutations in the tumor suppressor neurofibromatosis gene 2 (NF2) on chromosome 22q, while NF2-wildtype meningiomas account for about a third of all meningiomas." (PMID 35984495, 2022). "Some of the largest differences of SSTR expression were observed when comparing NF2 and sporadic meningioma tissue." (PMID 33899156, 2022). "Our report expands the spectrum of oncogenic YAP1 gene fusions an alternative to NF2 inactivation to include sporadic schwannoma, analogous to what has recently been described in NF2-wildtype pediatric meningiomas." (PMID 35986430, 2022).
meningioma (continued). "NF2-altered tumors are mainly localized at the convexity or in the lateral and posterior skull base; SMO-mutated meningiomas arise in the olfactory groove, while those with AKT1 and PIK3CA mutations are mostly found in the anterior and middle skull base." (PMID 35049691, 2022). "Multiple meningiomas are rare and have mostly been described in patients with neurofibromatosis type 2 (NF2)." (PMID 35308751, 2022). "We found the expression profiling experiment dataset (GSE156211: “Functional genomics of non-NF2 meningioma development and progression [RNA-seq]”) (A. Sablina, VIB-KU Leuven Center for Cancer Biology in Leuven, Belgium)." (PMID 35996584, 2022). "explored the immunological landscape of meningiomas in an NF2-mutant murine meningioma model and found that these tumors were heavily infiltrated by anti-inflammatory M2 macrophages." (PMID 35712491, 2022). "The case that was classified into Mal MC (Patient 11) showed multiple losses including 1p, 8p, 10, 14, 22q, as well as NF2 truncating mutation and homozygous deletion of CDKN2A/B, alterations commonly seen in atypical and anaplastic meningiomas." (PMID 35440040, 2022). "NF2 patients develop nervous system tumors, most commonly schwannomas (vestibular or of other cranial or peripheral nerves) but also meningiomas and ependymomas." (PMID 35053664, 2022). "Clinical connotation of NF2 alteration in terms of prognosis of WHO grade I meningioma differs in an opposite way between supratentorial and infratentorial tumors." (PMID 35570314, 2022). "Research found that FAM118B promotes NF2 wild-type meningiomas through the formation of YAP-FAM118B fusion genes." (PMID 36134026, 2022). "Monosomy 22 sequences and neurofibromatosis type 2 (NF2) are the most well-known genetic alterations founded in meningiomas." (PMID 36538194, 2022). "Overall, NF2 alterations are present in 70–80% of grade 2–3 meningiomas and 40% of grade 1 meningiomas." (PMID 36497370, 2022). "The largest difference was seen in SSTR1 with NF2 tumors reaching a mean score of 4.6 compared to 6.7 of sporadic meningiomas (p < 0.0001)." (PMID 33899156, 2022). "Although its role in meningioma genesis is still unclear, high OGN mRNA levels with NF2 or chromosome 22 loss have been identified." (PMID 35892898, 2022). "Supratentorial NF2 meningiomas had higher Ki-67 and forkhead box protein M1 expression than those of others, possibly explaining the worse prognosis in this subtype." (PMID 35570314, 2022). "For NF2, priority was assigned to the group tumour manifestations (vestibular schwannoma, meningioma and ependymoma)." (PMID 33903738, 2021). "Two NF2 unaltered meningiomas, localized at the olfactory groove and brain-invasive, had AKT1 E17K mutation." (PMID 33670055, 2021). "In line with the previous findings, NF2-mutant meningiomas represent the largest percentage (59%) of cases in our study." (PMID 34778063, 2021). "Mutations in TRAF7 have been identified in nearly one-fourth of meningiomas, while mutations in AKT1 and SMO have lower prevalence and are associated with higher grade NF2 wild-type tumors." (PMID 34300316, 2021). "NF2 transcript levels were downregulated in NF2-mutant meningioma samples, respectively (adjusted p = 1.10e-14)." (PMID 33319313, 2021). "A meta-analysis compiling data from 677 pediatric and adolescent meningioma patients showed that patients with NF2 had worse recurrence-free survival (RFS) time than patients without." (PMID 34495383, 2021). "One study showed that pediatric meningiomas harbored NF2 deletions frequently (82%) along with more aggressive histological features (high mitotic count, brain invasion)." (PMID 34495383, 2021). "Our findings indicated that chrysophanol inhibits OGN/mTOR signaling but induces NF2 signaling in meningioma cells." (PMID 33622177, 2021). "Patients with NF2 also develop meningiomas and less commonly, spinal schwannomas, ependymomas, and astrocytomas." (PMID 34604034, 2021).